GFRA3 (GDNF family receptor alpha 3)
Description:
Receptor for artemin (ARTN), a growth factor that supports the survival of sensory and sympathetic peripheral neurons. ARTN-binding leads to autophosphorylation and activation of the RET receptor.
Synonyms: GFRa-3; GDNFR3
Tractability: Antibody: UniProt places it where antibodies can reach, with high confidence; its Gene Ontology location is reachable by antibodies, with high confidence; UniProt predicts a signal peptide or a membrane-spanning region; the Human Protein Atlas places it where antibodies can reach.
Target class: Membrane receptor
Gene: Protein-coding gene on chromosome 5 (138,252,380 to 138,274,621, reverse strand). Ensembl gene ENSG00000146013.
Subcellular location: Cell membrane
Subcellular location (Human Protein Atlas): Plasma membrane; Cytosol
Pathways (Reactome):
Developmental Biology: RET signaling
Signal Transduction: RAF/MAP kinase cascade
Gene Ontology:
Molecular function: glial cell-derived neurotrophic factor receptor activity; protein binding; signaling receptor activity; signaling receptor binding; axon guidance receptor activity
Biological process: glial cell-derived neurotrophic factor receptor signaling pathway; nervous system development; peripheral nervous system development; signal transduction; axon guidance
Cellular component: plasma membrane; external side of plasma membrane; extrinsic component of membrane; receptor complex
Genetic constraint (gnomAD): Loss-of-function variants: 14 observed, 26.4 expected, observed/expected ratio (o/e) 0.53, 90% interval 0.35 to 0.83. The upper end of that interval is the gene's LOEUF score, 0.83, which puts it in group 3 of 6, group 1 being the genes least tolerant of losing a copy. Missense variants: 308 observed, 406.55 expected, observed/expected ratio (o/e) 0.76, 90% interval 0.69 to 0.83. Synonymous variants: 167 observed, 167.29 expected, observed/expected ratio (o/e) 1, 90% interval 0.88 to 1.13.
Homologues: Orthologues: chimpanzee GFRA3 (99% identical), macaque GFRA3 (97% identical), dog CDC23 (76% identical), mouse Gfra3 (76% identical), rat Gfra3 (75% identical), guinea pig GFRA3 (74% identical), rabbit GFRA3 (74% identical), pig GFRA3 (67% identical), zebrafish gfra3 (33% identical), Caenorhabditis elegans Y69A2AR.31 (26% identical), Drosophila melanogaster Gfrl (25% identical). Paralogues in human: GFRA1 (33% identical), GFRA2 (32% identical), GFRA4 (24% identical), GFRAL (20% identical).
Diseases named in the same sentence as GFRA3 in open-access papers:
GFRA3 is named in the same sentence as 33 diseases in open-access papers, as found by Europe PMC text mining. Sharing a sentence is not in itself a finding about the gene and the disease. The quoted sentences say what the papers report.
breast carcinoma (5 papers, 2013 to 2025). "Moreover, both GFRα1 and GFRα3 expression were significantly associated with survival outcome of patients with mammary carcinoma by univariate and multivariate analyses, whereas expression of SDC3 was not." (PMID 23351331, 2013). "In breast cancer, increased expression of GFRA3 was associated with lymph node metastasis and advanced tumor stage." (PMID 26984265, 2016). "Furthermore, significant association of GFRα1 and GFRα3 expression with survival outcome observed herein were restricted to ER negative or HER-2 negative mammary carcinoma." (PMID 23351331, 2013). "Survival analysis was performed to explore the correlation between the 4 DEGs (GFRA3, NPY1R, PTPRN2 and GABRP) with patients’ survival in over 400 breast cancer samples from TCGA database." (PMID 29423105, 2018). "We determined the mRNA and protein expression of three proteins demonstrated to bind ARTN, namely GFRα1, GFRα3 and Syndecan-3 (SDC3), in benign breast disease and mammary carcinoma by in situ hybridization and immunohistochemistry, respectively." (PMID 23351331, 2013). "The expression of GFRα1 and/or GFRα3, especially when combined with ARTN expression, may be useful predictors of disease progression and outcome in specific subtypes of mammary carcinoma." (PMID 23351331, 2013). "The expression of GFRα1 and GFRα3, but not SDC3, was significantly increased in mammary carcinoma and positively associated with tumor lymph node metastases, higher clinical stage and HER-2 positivity." (PMID 23351331, 2013). "Co-expression of ARTN with either GFRα1 or GFRα3, but not SDC3, produced synergistic increases in the odds ratio for both relapse-free and overall survival in patients with mammary carcinoma." (PMID 23351331, 2013).
gastric cancer (5 papers, 2011 to 2022). A primary or metastatic malignant neoplasm involving the stomach. "Methylation of the GFRA3 promoter has been linked to worse postoperative survival rates in patients with gastric cancer." (PMID 36353226, 2022). "Additionally, genome-wide DNA methylation profiling showed that GFRA3 promoter methylation was negatively correlated with gastric cancer prognosis." (PMID 35646712, 2022).
osteoarthritis (5 papers, 2020 to 2026). A noninflammatory degenerative joint disease occurring chiefly in older persons, characterized by degeneration of the articular cartilage, hypertrophy of bone at the margins and changes in the synovial membrane. "Some studies suggest that ARTN/GFRα3 signaling is involved in the pathogenesis of bone pain, and inhibition of this process could be used to treat pain in osteoarthritis (OA) when pathological features are present in the subchondral bone." (PMID 39091505, 2024).
hepatocellular carcinoma (2 papers, 2020). A malignant tumor that arises from hepatocytes. "Using hepatocellular carcinoma (HCC) tissues from in HCC patients, the protein levels of GFRa3 and phosphorylated RET were examined by immunohistochemistry (IHC) with automated cell acquisition." (PMID 32573073, 2020). "GFLs are also linked with hepatocellular carcinoma (HCC), as high expression of GFRα3 or phosphorylation of Ret in HCC tissues and an increase of ARTN in the serum correlate with poor prognosis in HCC patients." (PMID 32252363, 2020).
lymph node metastasis (2 papers, 2013 to 2016). "We have however described a clear metastasis promoting role for ARTN in ER negative MC consistent with the association of GFRα1 and GFRα3 expression with lymph node metastasis observed in this study." (PMID 23351331, 2013). "Thirdly, there were statistically significant, although slightly weaker positive correlations between GFRA3, ∆β and lymph node metastasis (p = 0.028), the degree of gastric mucosa metaplasia (0.044) and also patient age at surgery (p = 0.038)." (PMID 26984265, 2016). "The association between GFRA3, IL-8 and CLDN1 and the clinical features such as post-operative survival, lymph node metastasis, gastric metaplasia and patient age may describe a more complex relationship which we have not further evaluated in this study." (PMID 26984265, 2016).
migraine (2 papers, 2016 to 2024). "Thus, the role of the TRPV1 in migraine pain is still controversial to date, and the downstream regulatory mechanisms underlying the actions of artemin and GFRα3 on migraine pain require to be studied further." (PMID 27600145, 2016). "In this study, we explored the locations and expression of artemin and its selective receptor GFRα3 in an animal model of migraine, with special attention given to their possible involvement in the pathogenesis of migraine." (PMID 27600145, 2016). "In this regard, the present study was designed to evaluate the expression of artemin in the dura mater and GFRα3 in the TG following NTG administration, so as to explore the possible mechanisms of artemin and GFRα3 underlying the pathogenesis of migraine." (PMID 27600145, 2016). "The findings suggest that artemin and GFRα3 play an important role in the pathogenesis of migraine and may represent potential therapeutic targets for the treatment of migraine." (PMID 27600145, 2016). "Taken together, artemin and its selective receptor GFRα3 might be novel targets for therapeutic strategies of migraine." (PMID 27600145, 2016). "The distribution of artemin and GFRα3 in the dura mater raises an anatomy supports that they may be involved in migraine." (PMID 27600145, 2016). "In summary, our study revealed that the enhanced activities of artemin and GFRα3 might be critical processes in migraine pathogenesis and serve as the possible key factor in inducing migraine pain." (PMID 27600145, 2016). "In this study we evaluated the expression of artemin and GFRα3 in an animal migraine model that may be relevant for migraine." (PMID 27600145, 2016). "In addition, the detection of the distribution of artemin and its receptor GFRα3 in the dura mater of rats suggests that artemin may contribute to migraine pain by the sensitization of dural afferents." (PMID 27600145, 2016). "By binding to GFRα3, one of the GDNF family receptors, ARTN could exert an impact on intracellular signaling pathways that are crucial in the pathophysiology of bone pain and migraine." (PMID 39508645, 2024). "Meanwhile, the number of GFRα3 immunoreactive TG neurons was increased after NTG treatment, indicating that the release of artemin from the vascular smooth muscle cells may activate the peripheral trigeminal nerve via binding GFRα3 in a rat migraine model." (PMID 27600145, 2016).
non-small cell lung carcinoma (2 papers, 2016 to 2022). A group of at least three distinct histological types of lung cancer, including non-small cell squamous cell carcinoma, adenocarcinoma, and large cell carcinoma. "In pancreatic cancer GFRA3 may be implicated in the promotion of the disease through increased cell motility and invasiveness, and this gene is also up regulated in non-small cell lung cancer." (PMID 26984265, 2016). "ARTN, RET, and GFRα3 have been demonstrated to be upregulated in non-small cell lung carcinoma (NSCLC) cells compared with their normal counterparts, while high ARTN expression also enhances the migration and invasion of NSCLC cells." (PMID 35582425, 2022).
Arthritis (1 paper, 2022). Inflammation of a joint. "Our results provide a molecular basis of arthritis pain linked with artemin/GFRα3 signaling and indicate that further work is warranted to investigate the neuronal plasticity and the pathways that drive pain in OA." (PMID 35153665, 2022). "However, the role of GFRα3 signaling in arthritis pain has not been investigated to date." (PMID 35153665, 2022).
benign breast disease (1 paper, 2013). "We first utilized ISH to determine the expression of GFRα1, GFRα3 and SDC3 mRNA in mammary tissue from benign breast disease (BBD) and MC." (PMID 23351331, 2013).
cognitive disorder (1 paper, 2008). A disease affects cognitive processes. "Deficiencies in GFRA3 would be expected to cause cognitive impairment making it a candidate gene for cognitive disorders." (PMID 18837980, 2008).
colon tumors (1 paper, 2018). "Interestingly, ARTN, NRTN, GFRα1, and GFRα3 are found in colon tumors, potentially arising from gut nerves or associated with chronic inflammation of the intestine, which increases cancer risk, suggesting a subset of RET-expressing colon tumors may be responsive to GFL stimulation." (PMID 30666215, 2018).
craniopharyngioma (1 paper, 2020). A benign, partly cystic, epithelial tumor of the sellar region, presumably derived from Rathke pouch epithelium. "We know that RET and GFRα3 expression is lost in craniopharyngiomas, a pituitary benign neoplasia possibly derived of some stem cell population where β-catenin activation and nuclear localization, either through mutation or BRAF kinase activation, has been described." (PMID 33071961, 2020).
disc degeneration (1 paper, 2023). "In the current study, the percentages of ARTN- and PSPN-expressing cells increased in the advanced stage of disc degeneration; however, the percentages of cells expressing their cognate co-receptors (GFRA3 and GFRA4, respectively) did not increase." (PMID 37958856, 2023).
gastric atrophy (1 paper, 2016). "Secondly, a strong, and highly statistically significant positive relationship was identified between GFRA3 ∆β and gastric atrophy (p < 0.001)." (PMID 26984265, 2016).
liver cancer (1 paper, 2022). An epithelial or non-epithelial malignant neoplasm that arises from the liver. "CHRNE, GFRA2, GFRA3, and GRIN2D may serve as potential biomarker for liver cancer prognosis or immune response." (PMID 35646712, 2022).
lung carcinoma (1 paper, 2024). "We further observed that low-DRAIC/low-AKR7L and low-DRAIC/low-GFRA3 were also associated with poor survival outcomes (p < 0.05) in both lung cancer types." (PMID 39410631, 2024).
neuroblastoma (1 paper, 2017). Neuroblastoma (NB) is the most common solid, extracranial childhood tumor. "Specifically, we found that, for MYCN amplified neuroblastoma, pairwise expression of ACVR2B or anaplastic lymphoma kinase (ALK) with GFRA3, GFRA2, Cadherin 24, or with one another provided the strongest hits." (PMID 28871274, 2017). "For MYCN, non-amplified stage 4 neuroblastoma, neurotrophic tyrosine kinase 1, or ALK paired with GFRA2, GFRA3, SSK1, GPR173, or with one another provided the most promising paired-hits." (PMID 28871274, 2017).
pancreatic ductal adenocarcinoma (1 paper, 2022). An infiltrating adenocarcinoma that arises from the epithelial cells of the pancreas. "On the other hand, GFRA3 promoted the proliferation and invasion of pancreatic ductal adenocarcinoma cells, and its expression was negatively correlated with urothelial carcinoma prognosis." (PMID 35646712, 2022).
schizophrenia (1 paper, 2024). A major psychotic disorder characterized by abnormalities in the perception or expression of reality. "rs11242417-G (intr) polymorphism in the artemin receptor GFRα3 gene (GFRA3) turned out to be associated with the schizophrenia predisposition." (PMID 38646100, 2024).
triple-negative breast carcinoma (1 paper, 2023). An invasive breast carcinoma which is negative for expression of estrogen receptor (ER), progesterone receptor (PR), and human epidermal growth factor receptor 2 (HER2). "KRT17 and GFRA3 were negatively correlated with LCK in triple-negative breast cancer, while they were positively correlated in other classifications, with the exception of KRT17, which was negatively correlated with LCK in normal-like tissues with the highest correlation level." (PMID 37686072, 2023).
tumor (11 papers, 2013 to 2024). "Further, patients with cancer who received local tumor ionizing radiation (IR) alongside PD-1 therapy exhibited IR-mediated reduction of Ter-cells, artemin, and GFRα3 (an artemin signaling partner associated with tumor regression)." (PMID 39474425, 2024). "Both the expression of GFRα1 and GFRα3 protein were significantly associated with tumor LNM (P = 0.001 and P = 0.006), higher clinical stage (P = 0.001 and P = 0.008) and HER-2 positive expression (P = 0.030 and P = 0.005) respectively." (PMID 23351331, 2013). "Next, we investigated for any potential association of tumor expression of mRNA or protein for GFRα1, GFRα3 and SDC3 with the clinicopathologic features of MC." (PMID 23351331, 2013). "The expression levels of ENTPD2, BARX1, and GFRA3 were higher in LUAD tumor samples than in normal para-tumor samples." (PMID 36353226, 2022). "In the mouse models, Ter-cell derived artemin promoted cancer progression, while artemin knockout, pharmacological inactivation, or tumor-restricted knockdown of its receptor GFRα3 delayed cancer progression." (PMID 36561751, 2022). "Controlling for age at surgery, tumor size and histological type, GFRA3 methylation level was still a highly significant (p = 0.01) predictor of survival." (PMID 26984265, 2016). "The strong association between expression of CLDN1 gene, methylation of GFRA3 promoter and expression of IL-8 gene in tumor tissue warrants further investigation in regards to the influence of H. pylori infection, but this is beyond the scope of this study." (PMID 26984265, 2016). "In addition, in cancer patients and tumor-bearing mice, radiotherapy reduced the level of Artemin in serum and the expression of GFRα3 in tumor tissues." (PMID 35799264, 2022). "However, in our analysis, GFRA2 exhibited an anti-tumor effect, while GFRA3 exerted a pro-tumor effect." (PMID 35646712, 2022). "Importantly, increase in serum artemin levels and elevated tumor expression of GFRα3 were also observed in human HCC patients and correlated with poor prognosis." (PMID 36561751, 2022). "Tumors, via the expression of GFRα1, GFRα2, GFRα3, respond to molecules released by nerves and, in an autocrine fashion, to molecules released by the tumor itself and these interactions are likely amplified in the tumor microenvironment." (PMID 32252363, 2020). "Therefore, a cell-type specific GFRα2/GFRα3 ratio could indeed determine the tumor promoting vs. tumor suppressing behavior of RET." (PMID 34716856, 2022). "The expression of KHDRBS2 and MYOZ1 was downregulated in the LUAD cancer samples compared with that in the para-tumor normal samples, whereas the expression of BARX1, ENTPD2, and GFRA3 was upregulated in LUAD cancer tissues." (PMID 36353226, 2022). "We next determined if the worse survival outcome in patients with tumors with co-expression of either GFRα1 or GFRα3 and ARTN was restricted to tumor subtypes." (PMID 23351331, 2013).
cancer (10 papers, 2011 to 2024). A tumor composed of atypical neoplastic, often pleomorphic cells that invade other tissues. "When an initial damage to the nerves by cancer cell, neurons and/or SCs produce Artemin/GFRα3 to repair the nerves, but the abundance of Artemin attracts further cancer cells to the site of injury, which produces a vicious cycle." (PMID 36900158, 2023). "Hypermethylation has already been reported for PAX5, KCNAB3, MEIS2 and GFRA3 in different cancer entities." (PMID 28634396, 2017). "Moderate or strong expression of GFRα1 and GFRα3 mRNA was predominantly localized in the carcinoma cells with an infrequently positive signal located in stromal cells." (PMID 23351331, 2013). "GFRA3 may play different roles in the two cancer types, however a larger study is necessary to clarify whether there exists a true difference between the methylation of this gene in the two histological types and its significance." (PMID 26984265, 2016). "GFRA2 and GFRA3 were glial cell line-derived neurotrophic factor (GDNF) receptors, and previous studies have suggested their participation in cancer." (PMID 35646712, 2022). "Similar to mRNA expression, GFRα1, GFRα3 and SDC3 proteins were localized in the cytoplasm of epithelial cells of mammary ducts and acini in BBD or carcinoma cells in MC." (PMID 23351331, 2013). "A few genes were found to be in both the cancer grading and staging signatures, such as CPS1, DES, GFRA3, TMED6 and DPT, indicating some biological relevance between cancer differentiation and progression." (PMID 21445269, 2011).
GFRA3 also shares sentences with these, for which no sentence is quoted: pancreatic cancer (2 papers); asthma (1); bone cancer (1); chronic pancreatitis (1); Gastric Metaplasia (1); hepatitis B (1); knee osteoarthritis (1); leukemia (1); melanoma (1); osteomyelitis (1); urothelial carcinoma (1).